TRPV6 (transient receptor potential cation channel subfamily V member 6)
Diseases named in the same sentence as TRPV6 in open-access papers (continued):
Sharing a sentence is not in itself a finding about the gene and the disease.
breast carcinoma (continued). "In other tumour entities, TRPV6 was also correlated with high proliferation rate of the prostate and breast cancer cells, as the calcium conductance activates the calcium/ calmodulin/calcineurin dependent transcription factor NFAT affecting the expression of the cell-cycle regulators." (PMID 32228510, 2020). "Indeed, suppression of basal Ca2+ influx increases the effect of other cancer agents, as seen with the promotion of tamoxifen‐induced cell death with TRPV6 silencing in T47D breast cancer cells." (PMID 31647602, 2020). "TRPV6 is widely upregulated in multiple malignant cells including breast cancer cells." (PMID 32211326, 2020). "Similarly, TRPV6 silencing in breast cancer cells with increased endogenous TRPV6 led to lower basal calcium influx and reduced proliferation." (PMID 32825277, 2020). "Importantly, tamoxifen, the widely used drug in breast cancer therapy, is more sensitive in reducing cell viability when TRPV6 is silenced." (PMID 32211326, 2020). "Though TRPV1, TRPV4, and TRPV6 all mediate calcium fluxes in breast cancer cells, their unique and even opposite functions in breast cancer progression suggest a complicated network of calcium signaling in modulation of tumor cell functions, which requires further efforts to elucidate." (PMID 32211326, 2020). "In breast cancer, TRPV6 is up-regulated, compared to adjacent, benign breast tissue." (PMID 32887395, 2020). "Such expression is correlated with a low survival rate in breast cancer patients, which might be ascribed to the essential role of TRPV6 in driving abnormal tumor cell proliferation." (PMID 32211326, 2020). "Further, TRPV6 protein is elevated in invasive tissues in 93% of 15 breast cancer biopsies such that the channel was again identified as a possible therapeutic target in breast cancer." (PMID 28150073, 2017). "Besides, TRPV6 is mainly over-expressed in the invasive breast cancer cells and selective silencing of TRPV6 inhibits migration and invasion of breast cancer." (PMID 26818094, 2016). "Importantly, 17β-oestradiol was demonstrated to increase breast cancer cell proliferation which show extremely high density of TRPV6 expression." (PMID 27450545, 2016). "Additionally, breast cancer patients with high expression of TRPV6 have a worse survival when compared to those with low or intermediate TRPV6 expression." (PMID 26818094, 2016). "Similarly, the expression of TRPV1 and TRV4 is elevated in human hepatoblastoma and breast cancer cells, respectively, and the expression level of TRPV6 correlates with tumor progression in prostate, thyroid, colon, ovarian, and breast cancers." (PMID 25710007, 2015). "Moreover, it is important to consider whether the tissue samples were collected from invasive or non-invasive parts of the tumor because TRPV6 has preponderant expression in the invasive areas of breast cancer." (PMID 36012311, 2022). "Moreover, TRPV6 expression was associated with increased levels of EMT markers, suggesting that either too low or too high expression of the channel can lead to the development of breast cancer." (PMID 34360952, 2021). "Altogether, these results strongly suggest that TRPV6 channels facilitate the calcium influx required for breast cancer cells to proliferate and survive, and that these channels are part of the molecular mechanism of the 17-β estradiol-induced proliferation in breast cancer cells." (PMID 32210800, 2020). "Therefore, TRPV6 could be a potential drug target that alleviate chemotherapeutic resistance in breast cancers." (PMID 32211326, 2020). "Furthermore, expression level of TRPV6 was tightly linked to the levels of common EMT markers, suggesting that TRPV6 may have a role in the mesenchymal invasion of breast cancer cells." (PMID 32895467, 2020). "Therefore, TRPV6 is suggested to be involved in the metastatic process of breast cancer." (PMID 29772843, 2018).
breast carcinoma (continued). "TRPC6 is being explored as a biomarker for cardiotoxicity in breast cancer (NCT05507879), while TRPV6 is currently in phase I trial for advanced ovarian cancers (NCT01578564)." (PMID 40813985, 2025). "TRPV6 silencing induced significant decrease in TRPV6 mRNA in both non-invasive (MCF-7) and invasive (MDA-MB-231) breast cancer cell lines." (PMID 32887395, 2020). "The findings suggest that TRPV6 activation enhances NFATc2’s transcriptional activity by modulating the phosphorylation of NFATc2IP, thereby promoting ADAMTS6 expression and facilitating metastasis in breast cancer." (PMID 40078961, 2025). "The strong correlation between TRPV6 expression levels and the levels of common EMT markers implies that TRPV6 may have a function in the mesenchymal invasion of breast cancer cells." (PMID 38534438, 2024). "Elevated TRPV6 and subsequent sustained increases in cytosolic calcium activates the nuclear factor of activated T-cells (NFAT) transcription factors in cell lines of prostate 96 and breast cancers." (PMID 31897233, 2020). "Unlike TRPV1 and TRPV4, TRPV6 has been shown to positively promote breast cancers progression." (PMID 32211326, 2020). "Moreover, TRPV6 silencing inhibits MDA-MB-231 and MCF-7 breast cancer cell migration." (PMID 29772843, 2018).
ovarian carcinoma (16 papers, 2013 to 2025). A malignant neoplasm originating from the surface ovarian epithelium. "According to a recent study, ovarian cancers of various grades—low-grade serous, high-grade serous, clear cell, endometrioid, and mucous—express more TRPV6 mRNA than normal tissues do." (PMID 38534438, 2024). "All five ovarian cancer disease types have been shown to have elevated TRPV6 mRNA levels in both their early and late stages when compared to healthy tissues." (PMID 38534438, 2024). "An early report that revealed an over-expressing TRPV6 channel in one biopsy report also mentioned ovarian cancer." (PMID 38534438, 2024). "Previous studies have shown that TRPV6 is overexpressed in various cancers, such as prostate, breast, colon, and ovarian cancers." (PMID 38136316, 2023). "Two C-terminus peptide sequences of soricidin (SOR-C13 and SOR-C27) were shown to bind specifically TRPV6 in ovarian cancer cells as well as ovarian cancer xenografts in mouse models." (PMID 37468801, 2023). "Immunohistochemical detection of TRPV6 protein in tissue microarrays for ovarian cancers likewise showed elevated protein in all cancer types and at early and late stages of the diseases with little (if any) in biopsies of healthy tissue." (PMID 31897233, 2020). "Elevated TRPV6 mRNA was reported in early and late stages of all five of the disease types classified under the umbrella of ovarian cancer when compared to healthy tissue." (PMID 31897233, 2020). "Soricidin and its derivatives (SOR-C13, 14 nM; and SOR-C27, 65 nM) inhibit TRPV6-dependent Ca2+ uptake and bind TRPV6 with a high affinity in ovarian cancer (OC)." (PMID 31801263, 2019). "TRPV6 mRNA and protein expression have been detected in ovarian cancer and other cancer types, such as breast, prostate, thyroid and colon cancer." (PMID 31627357, 2019). "The TRPV6 protein is over-expressed in carcinomas of ovary and other cancer such as breast, colon, prostate and thyroid." (PMID 23554944, 2013). "Subsequently, two peptide sequences from the C-terminus of soricidin (SOR-C13 and SOR-C27) were shown to bind TRPV6 in ovarian cancer cells with high affinity." (PMID 23554944, 2013). "TRPV6 is a calcium channel that is overexpressed in various cancers, and its inhibitors can lead to better treatment outcomes in patients with colorectal, pancreatic, and ovarian cancer." (PMID 41001032, 2025). "Consequently, prostate, colon, breast, thyroid, and ovary carcinomas exhibit much higher levels of TRPV6 channels in comparison to normal tissues or cells." (PMID 38534438, 2024). "However, TRPV6 is also aberrantly expressed in various cancers, such as prostate, breast, colon, and ovarian cancers." (PMID 38136316, 2023). "Similarly, lidocaine reduced TRPV6 expression, migration and invasion in TRPV6-positive breast, prostate and ovarian cancer cells." (PMID 34408981, 2021). "Concerning ovarian carcinoma cells, TRPV6, TRPC3 and T-type calcium channel are found to be overexpressed leading to think that these proteins could be considered as therapeutic targets." (PMID 25627260, 2015). "Besides the maintenance of Ca2+ balance in healthy tissues, overexpression of TRPV5/TRPV6 mRNA and proteins was observed in advanced stages of prostate, colon, breast, thyroid and ovarian carcinomas and leukaemia." (PMID 25164318, 2014). "Furthermore, SKOV-3 tumor xenografts in mice were shown to develop less when TRPV6 was targeted using TRPV6 peptide antagonists, supporting the idea that TRPV6 may be a key target for ovarian cancer treatments." (PMID 38534438, 2024). "The TRPV6 inhibitor SOR-C13 is already in Phase I clinical trials in patients with advanced solid cancers and is approved as an orphan drug for pancreatic and ovarian cancers." (PMID 37369706, 2023). "In ovarian cancer, TRPV6 has increased expression in all stages when compared to normal tissue." (PMID 38136316, 2023).
pancreatic cancer (14 papers, 2018 to 2024). "The ADM group was characterised by transient receptor potential vanilloid member 6 (TRPV6) promoter opening, implicated in promoting pancreatic cancer." (PMID 38426634, 2024). "The presence of TRPV6 is strongly associated with the progression and outcome of pancreatic cancer (PC), as patients with elevated levels of TRPV6 in their tumors have a poorer chance of survival." (PMID 38534438, 2024). "Elevated TRPV6 is associated with poor prognosis in pancreatic cancer; moreover, knockdown of TRPV6 decreased Bcl-2 and increased BAX in Capan-2 cells, inhibiting proliferation and migration, while promoting apoptosis." (PMID 32825277, 2020). "TRPV6 was recently implicated directly in development and prognosis of pancreatic cancer with decreased survival in patients with elevated tumour TRPV6 protein levels." (PMID 31897233, 2020). "Collectively, these results suggest that TRPV6 channels contribute to the resistance of pancreatic cancer cells to 5-FU and gemcitabine." (PMID 38136316, 2023). "In a Phase I clinical trial of SOR-C13, a TRPV6 calcium channel inhibitor, two patients having advanced pancreatic cancer indicated a reduction in tumor, along with a 55% reduction in CA19–9 in one patient." (PMID 36371178, 2022). "A positive expression of the TRPV6 protein and mRNA level was significantly upregulated in pancreatic cancer tissues and was correlated with unfavorable patient survival rates." (PMID 36012311, 2022). "Ovarian, prostate and pancreatic cancers are particularly noted because a large proportion of the tumors (>90%) consistently express TRPV6 mRNA well above normal levels." (PMID 31897233, 2020). "The knockdown of TRPV6 in pancreatic cancer cell lines resulted in a reduced proliferation, induced cell cycle arrest in the G0/G1 phase, reduced migration and invasion, as well as increased apoptosis." (PMID 32182937, 2020). "TRPV6 is upregulated in human pancreatic cancer specimens and silencing of TRPV6 significantly inhibits invasion, proliferation and migration of pancreatic cancer cells." (PMID 29772843, 2018). "This confirms that TRPV6 may mediate resistance to 5-FU and, possibly, gemcitabine in pancreatic cancer cells." (PMID 38136316, 2023). "Consistent with the GEPIA results, the expression levels of TRPA1, TRPM8, TCAF1, and TCAF2 were significantly higher in pancreatic cancer tissue (p < 0.001), and TRPV6 expression was significantly lower in pancreatic cancer tissue compared to normal tissues (p < 0.001)." (PMID 36012311, 2022). "Adding to the fact that TRPV6 is also linked to early onset chronic pancreatitis, a risk factor for the development of PDAC, makes it indispensable to undertake a more detailed analysis of TRPV6 channels in pancreatic cancer." (PMID 33925979, 2021). "Additionally, high TRPV6 is linked to increased levels of anti-apoptotic Bcl-232 and downregulation of TRPV6 with specific siRNAs in pancreatic cancer cells led to significant decrease in Bcl-2, concomitant with triggered apoptosis." (PMID 32895467, 2020). "This suggests that TRPV6 may confer resistance to 5-FU in pancreatic cancer cells." (PMID 38136316, 2023). "Thus, TRPV6 has pleiotropic effects in pancreatic cancer, which may depend on the type of cancer and tumor microenvironment." (PMID 36371178, 2022). "Further studies are needed to elucidate the molecular mechanisms through which TRPV6 regulates PDAC aggressiveness and to evaluate the therapeutic potential of TRPV6 inhibitors in other PDAC models, like pancreatic cancer organoids." (PMID 38136316, 2023). "First, using the GEPIA web platform as a bioinformatic tool, we explored the transcriptional levels of TRPV6, TRPA1, TRPM8, TCAF1, and TCAF2 in pancreatic cancer (n = 179) and normal pancreatic tissues (n = 171)." (PMID 36012311, 2022).
pancreatic cancer (continued). "First, we queried GEPIA to explore the relationship between the TRPV6, TRPA1, TRPM8, TCAF1, and TCAF2 mRNA expressions and sub-stages in pancreatic cancer samples, compared to the control (normal subjects)." (PMID 36012311, 2022). "Next, we used UCSC Xena to explore the expression levels of TRPV6, TRPA1, TCAF1, TCAF2, and TRPM8 in pancreatic cancer (n = 178) and in normal pancreatic tissue (n = 167)." (PMID 36012311, 2022). "TRPV6 inhibition aims to suppress Ca2+-mediated cancer proliferation and metastasis e.g., in SCLC, prostate or pancreas cancer." (PMID 29772843, 2018). "However, another study found that low TRPV6 expression was associated with advanced TNM stage, lymph node metastasis and distant metastasis, indicating the anti-oncogenic role of TRPV6 in pancreatic cancer." (PMID 36371178, 2022). "Furthermore, TRPV6 protein expression is elevated in pancreatic cancer tumors compared to non-tumor adjacent tissues and its high expression correlated with lower survival of the patients." (PMID 32182937, 2020).
colon carcinoma (9 papers, 2011 to 2024). "TRPV6 channel overexpression has been linked to early-stage colon cancer, while the suppression of TRPV6 has hindered cell growth and triggered programmed cell death in colon carcinoma cells." (PMID 38534438, 2024). "Dietary calcium has been shown to reduce the risk of colon cancer, and Ca2+ intake in a high-calcium diet may require the inhibition of TRPV6 to have a protective effect on the colon." (PMID 38534438, 2024). "Increased levels of colonic TRPV6 are associated with early-stage colon cancer." (PMID 21420431, 2011). "TRPV6 regulates colon cancer by enhancing the IGF-induced PI3K-PDK1-Akt signaling pathway in human colon cancer." (PMID 38534438, 2024). "It has been demonstrated that both human colon cancer cell proliferation and colonic crypt hyperplasia in mice are influenced by abnormal TRPV6 expression." (PMID 38534438, 2024). "In contrast, it has been observed that the expression of TRPV6 in colon cancer cells is elevated due to enhanced vitamin D signaling through p38α and GADD45α in the colorectal cell line SW480." (PMID 38534438, 2024). "In zebrafish epithelia and human colon carcinoma cells, Trpv6/TRPV6 elevated intracellular Ca2+ levels and activated PP2A, which down-regulated IGF signaling and promoted the quiescent state." (PMID 31526479, 2019). "The TRPV6-[Ca2+]i-PP2A signaling axis appears to be conserved in human colon carcinoma cells because siRNA-mediated knockdown or inhibition of TRPV6 increased LoVo cell proliferation." (PMID 31526479, 2019). "While TRPV5 occurs primarily in the kidneys, TRPV6 is predominantly expressed in intestinal epithelial cells and has also been localized to human colon cancer (Caco-2) cells." (PMID 21420431, 2011). "While the exact mechanism of action of TRPV6 in colon cancer remains unknown, new research has shown that invasive qualities appear to be conferred on colon cancer cells by changes in TRPV6′s binding structure to CaM." (PMID 38534438, 2024). "Other independent study revealed that TRPV6 might mediate growth factor signaling to induce PI3K-PKD1-AKT cascade via calcium in human colon cancer." (PMID 30881453, 2019). "Curcumin, which is a ligand of 1,25-vitamin D3 receptor that up-regulated TRPV6 in vivo, may play a role similar to that of 1,25-vitamin D3 in promoting calcium uptake as part of the protective effect against colon cancer." (PMID 26818094, 2016). "On the other hand, however, some studies indicated that TRPV6 might play antitumour role in some cancer types, such as colon cancer." (PMID 26818094, 2016). "The inhibitory effect of TNFα on CYP27B1 and TRPV6 expression in colon cancer cells might alter calcium uptake in the inflamed intestine." (PMID 24120915, 2014). "TRPV6 in the intestinal epithelium also appears to have a bearing on colon cancer development." (PMID 21420431, 2011). "Together with experiments in mice with colon crypt hyperplasia, these findings indicate that TRPV6 promotes the proliferation of colonic epithelial cells and may be a pathogenetic factor in the early stages of colon cancer development." (PMID 21420431, 2011). "Future studies are needed to clarify the role of TRPV6-[Ca2+]i-PP2A in prostate and colon cancer initiation and progression and its relationship to IGF signaling." (PMID 31526479, 2019). "Knockdown and inhibition of TRPV6 and PP2A increases human colon carcinoma cell proliferation." (PMID 31526479, 2019). "Thus, blockade of TRPV6 can be considered as a measure to prevent and inhibit the development of colon cancer, but this effect needs to be balanced against any negative impact on calcium homeostasis." (PMID 21420431, 2011).